RNU7-57P (RNA, U7 small nuclear 57 pseudogene)
Synonyms: U7.57
Gene: Small nuclear RNA gene on chromosome 1 (154,338,743 to 154,338,802, forward strand). Ensembl gene ENSG00000238365.
Homologues: Orthologues: macaque U7 (88% identical). Paralogues in human: RNU7-60P (90% identical), U7 (90% identical), RNU7-124P (88% identical), RNU7-13P (88% identical), RNU7-171P (88% identical), RNU7-25P (88% identical), RNU7-48P (88% identical), RNU7-88P (88% identical), U7 (88% identical), RNU7-2P (87% identical), RNU7-35P (87% identical), RNU7-41P (87% identical), and 143 more.